KEAP1 (kelch like ECH associated protein 1)
Diseases named in the same sentence as KEAP1 in open-access papers (continued):
Sharing a sentence is not in itself a finding about the gene and the disease.
depression (continued). "Alterations in Keap1 and Nrf2 have also been observed in rodent models of depression." (PMID 36552553, 2022). "A recent study using postmortem brain samples exhibited reduced Keap1 and Nrf2 expression levels in the parietal cortex of depressed patients, suggesting that decreased Keap1-Nrf2 signaling plays a role in depression." (PMID 30135655, 2018). "Moreover, the protein expressions of Keap1 and Nrf2 in the parietal cortex from major depressive disorder and bipolar disorder were lower than controls." (PMID 30386243, 2018). "All these findings implicate the Keap1-Nrf2 system in the pathophysiology of depression, as well as suggesting that the dietary intake of 0.1% GF pellets during juvenile and adolescent development may confer stress resilience in adulthood." (PMID 27470577, 2016). "Notably, however, changes in Keap1-Nrf2 signalling have been observed in postmortem brain tissue from patients with major depressive disorder and bipolar disorder which showed marked reductions in protein levels of Keap1 and Nrf2 in the parietal cortex compared to the control group." (PMID 36552553, 2022). "Furthermore, the expression of Keap1 and Nrf2 proteins in the parietal cortex of depressed patients was lower than that in controls, suggesting that Keap1-Nrf2 signaling contributes to stress resilience, which plays a key role in the pathophysiology of depression." (PMID 30135655, 2018). "As a result, it can be anticipated that the communication between Keap1-Nrf2 signaling and BDNF-TrkB signaling in the brain plays an important role in depression." (PMID 40149774, 2025). "Human postmortem samples from major depressive disorder, SCZ, and BP exhibited significantly lower KEAP1 and NRF2 in the parietal cortex compared to controls." (PMID 39723615, 2024). "Overall, our study verified that during states of excessive oxidative stress, the PIK3CA/AKT1/NFE2L2/KEAP1 and PIK3CA/AKT1/BDNF/NTRK2 signaling pathways are suppressed, which induced OB rats to exhibit phenotypic behaviors of depression." (PMID 33935736, 2021). "We reported decreased expression of Nrf2 and Keap1 in the parietal cortex from MDD patients compared with that from the control group, which indicates that decreased Keap1–Nrf2 signaling may play a crucial role in the development of depression." (PMID 33627628, 2021). "In the learned helplessness paradigm, the protein levels of Keap1 and Nrf2 in the PFC and DG of hippocampus from rats with depression-like phenotype were also lower than control and resilient rats." (PMID 30386243, 2018). "Preclinical studies demonstrated that the protein expressions of Keap1 and Nrf2 in the prefrontal cortex (PFC), CA3 and dentate gyrus (DG) of hippocampus in mice with depression-like phenotype were lower than control mice." (PMID 30386243, 2018). "We found lower expression of Keap1 and Nrf2 proteins in the prefrontal cortex (PFC), CA3 and dentate gyrus (DG) of hippocampus in mice with depression-like phenotype compared to control mice." (PMID 27470577, 2016). "In conclusion, our study demonstrated that not only is the Keap1-Nrf2 system crucial to the pathophysiology of depression, but that decreased BDNF-TrkB signaling in the PFC, CA3, and DG plays a role in the depression-like phenotype of Nrf2 KO mice." (PMID 27470577, 2016). "In addition, this is the first study to establish the role of Keap1-Nrf2 signaling in the prophylactic and therapeutic effects of SFN in the comorbidity of neuropathic pain and depression in rodents." (PMID 30135655, 2018). "Once Nrf2 is activated, Keap1 is released from Nrf2 and promotes nuclear translocation of Nrf2, activating the downstream target proteins HO-1, SOD1, GCLC, and GCLM, thus playing a key role in anti-inflammatory and anti-oxidative stress activities of depression." (PMID 40308754, 2025). "Therefore, it is likely that the communication between Keap1–Nrf2 signaling and BDNF–TrkB signaling in the brain might play a crucial role in depression." (PMID 33627628, 2021).
depression (continued). "Furthermore, SFN could attenuate the decreased levels of Nrf2 and Keap1 proteins in the PFC and hippocampus of mice with depression-like phenotype." (PMID 30386243, 2018).
neuroblastoma (21 papers, 2012 to 2025). Neuroblastoma (NB) is the most common solid, extracranial childhood tumor. "In the present study we show that CBR-470-1 activates the Nrf2 cascade in SH-SY5Y neuroblastoma cells, causing disassociation of the Keap1-Nrf2 complex, cytosol Nrf2 protein stabilization and nuclear translocation, followed by increased expression of Nrf2 pathway genes (HMOX1, NQO1 and SOD1)." (PMID 32649311, 2020). "Although there is no direct proof of chromatin structure alterations in either NFE2L2 or KEAP-1 in neuroblastoma, there are a few studies supporting potential epigenetic modifications of both genes." (PMID 38666930, 2024). "Overexpression of the TAU P301S mutant protein in a mouse neuroblastoma cell line and primary hippocampal neurons increases KEAP1 levels and enhances KEAP1 K312 acetylation, resulting in reduced NRF2 levels in both the hippocampus and primary neurons." (PMID 39765857, 2024). "MiR-7 also activates NRF2 by targeting KEAP1 expression in human SH-SY5Y neuroblastoma cells, resulting in increased levels of the reduced form of GSH, indicative of OS mitigation." (PMID 34663413, 2021). "miR-7 relieves the oxidative stress of neuroblastoma cells by targeting KEAP1, which promotes an increased expression of NRF2 and the transcription of antioxidant genes such as HO-1 and GLCGM." (PMID 32492865, 2020). "In SH-SY5Y neuroblastoma cells and differentiated human neural progenitor cells, miR-7 activated Nrf2 signaling by targeting and silencing Keap1." (PMID 32102665, 2020). "The use of 5 ́-aza may also be considered in neuroblastoma treatment due to its regulatory effect on the activity of both KEAP-1 and PHOX2B promoters." (PMID 38666930, 2024). "Thus, the mechanism of the flavonoids against MG-induced oxidative stress in PC-12 neuroblastoma cells was studied through a Western blot analysis of the Nrf2/Keap1/HO-1 signaling pathway." (PMID 36431904, 2022). "In another research, authors concluded that withaferin A can kill tumors in high-risk neuroblastoma via KEAP1 -Nrf2 axis, a noncanonical ferroptosis pathway." (PMID 34244461, 2021). "Here we examine whether activation of the Keap1-Nrf2 cascade can protect SH-SY5Y neuroblastoma cells from MPP+-induced cytotoxicity." (PMID 32649311, 2020). "One example is the regulation of KEAP1 in neuroblastoma cells." (PMID 32492865, 2020). "Besides OxyR, the signaling pathway of Keap1/Nrf2 responding to antioxidants is also regulated by polysulfides in mouse neuroblastoma cells." (PMID 31421411, 2019). "Besides, withaferin A can kill tumors in high-risk neuroblastoma via Kelch-like ECH-associated protein 1 (KEAP1) -Nrf2 axis, a noncanonical ferroptosis pathway." (PMID 34244461, 2021). "Subsequently, Mahimainathan’s group identified and validated for the first time a series of miRNAs, miR-153, miR27a, miR142-5p, and also miR-144 in neuronal cells, specifically in human SH-SY5Y neuroblastoma cells, which directly mediate repression of NFE2L2 in a KEAP1-independent manner." (PMID 34663413, 2021).
Cognitive impairment (20 papers, 2015 to 2026). Abnormal cognition is characterized by deficits in thinking, reasoning, or remembering. "The current study reveals that Prob, a phenolic lipid-lowering agent, holds the potential to ameliorate cognitive impairment and neuronal loss in D-gal-induced aging mice by attenuating oxidative stress via Keap1/Nrf2-mediated pathway." (PMID 31590160, 2019). "Our findings align with a prior study, which reported that APS ameliorates cognitive impairment and β-amyloid accumulation in mice by activating the Nrf-2/Keap1 pathway." (PMID 40003935, 2025). "GAS has been shown to enhance the antioxidant capacity and inhibit ferroptosis through the Nrf2/Keap1-glutathione peroxidase 4 (GPx4) pathway, thus improving cognitive impairment in rats with VD." (PMID 39776583, 2024). "Overall, our study illustrated that AS-IV decreases the fasting blood glucose levels, alleviates oxidative stress and neuroinflammation, and ultimately improves cognitive impairment probably via Nrf2/Keap1/HO-1/NQO1 pathway in T2DM mice." (PMID 36247985, 2022). "Taken together, the current study presents that Prob has the potential to ameliorate D-galactose induced cognitive deficits by alleviating oxidative stress via Keap1/Nrf2 signaling pathway." (PMID 31590160, 2019). "In animal models, cognitive deficits were observed in memory and learning tasks, associated with increased oxidative stress and alterations in molecular pathways such as AMPK, HO-1, and nNOS/Keap1/Nrf2." (PMID 41150587, 2025). "Blocking the interaction between P301S and KEAP1 at K312 by a custom‐designed peptide could efficiently rescue P301S‐induced synaptic protein reduction and cognitive deficits in a manner dependent on NRF2 expression." (PMID 35917404, 2022). "Furthermore, we observed an epistatic gene effect of the NRF2 and KEAP1 genes on cognitive impairment in patients with schizophrenia." (PMID 26107664, 2015). "Moreover, the NRF2 gene and the KEAP1 gene had an epistatic effect on cognitive impairment (e.g., working memory and processing speed) in patients with schizophrenia." (PMID 26107664, 2015). "Therefore, in the present study, we explored the hypothesis that AS-IV might improve diabetes-related cognitive impairment in T2DM mice by modulating the Nrf2/Keap1/HO-1/NQO1 pathway." (PMID 36247985, 2022). "Thus, it seems that abnormalities in the Keap1-Nrf2 system in the hippocampus might play a role in the cognitive deficits seen in juvenile offspring after MIA." (PMID 29391571, 2018). "Several studies have reported that Keap1 mediated the regulation of Nrf-2 by SFN, and the Keap1/Nrf-2/ARE signaling pathway was involved in the early brain injury and secondary cognitive impairment following SAH." (PMID 40919572, 2025). "Taken together, these data suggested that AS-IV ameliorates cognitive impairment in T2DM mice by attenuating oxidative stress and neuroinflammation, possibly through modulating the Nrf2/Keap1/HO1/NQO1 pathway." (PMID 36247985, 2022). "Taken together, it is likely that MIA can interfere with Keap1-Nrf2 system and NMDA receptor in the hippocampus during brain development, resulting in cognitive deficits in juvenile and adult offspring." (PMID 29391571, 2018). "Mechanisms such as oxidative stress, mitochondrial dysfunction, neuroinflammation, neurotransmitter abnormality, and intestinal dysfunction can damage brain tissue by mediating Keap1/Nrf2/ARE, NF-κB, and other signal pathways, resulting in cognitive impairment." (PMID 36937345, 2023). "Pesticide-induced cognitive impairment is also accompanied by the regulation of NMDAR, PI3K/Akt, MAPK, Keap1/Nrf2/ARE, NF-κB, and other multiple learning and memory pathways, which can be formed into an organic whole through the crosslinking targets such as RAS, Akt, and IKK." (PMID 36937345, 2023).
Insulin resistance (19 papers, 2018 to 2024). Increased resistance towards insulin, that is, diminished effectiveness of insulin in reducing blood glucose levels. "Curcumin demonstrated Nrf2 activation by inhibiting the upregulation of Keap1 induced by inflammatory signals, thereby contributing to its antioxidant benefits and alleviating insulin resistance in high-fat-diet obese mice." (PMID 39770516, 2024). "Constitutively enhanced Nrf2 signaling induced by knocking down Keap1 prevents impaired metabolism and insulin resistance in lipodystrophic mice via inhibition of lipogenic enzymes in the liver." (PMID 32971975, 2020). "It has also been proposed that enhanced Nrf2 signaling by the Keap1 knockdown prevents hepatic steatosis, dyslipidemia, and insulin resistance." (PMID 32443555, 2020). "Curcumin promoted Nrf2 activity by disrupting the interaction between Keap1 and Nrf2 in renal epithelial cells and improved glucose intolerance and insulin resistance in HFD-induced obese mice." (PMID 29241092, 2018). "The Keap1-KD-mediated activation of this pathway reportedly reduces weight gain and improves insulin resistance in the short term (8–9 weeks) in HFD-fed mice; however, it conversely causes weight gain and the development of insulin resistance in the long-term in HFD-fed mice." (PMID 35610278, 2022). "Keap1-knockdown (KD) and Nrf2-knockout (KO) mice do not change insulin resistance since they lack the activity of the Nrf2/Keap1 systems." (PMID 35268403, 2022). "The present study demonstrated that dietary selenium could reverse liver damage and insulin resistance in the progression of NAFLD, and alleviated oxidative stress in hepatocytes through the KEAP1/NRF2 pathway." (PMID 35204232, 2022). "Functional genomic studies with tissue-selective activation of Nrf2 by partial knockdown of Keap1 in the obesogenic HFD-fed mouse model of insulin resistance indicated that selective activation of Nrf2 in skeletal muscle and the liver corrected insulin resistance and dysglycemia, respectively." (PMID 35269594, 2022).
multiple sclerosis (19 papers, 2014 to 2026). A progressive autoimmune disorder affecting the central nervous system resulting in demyelination. "Cysteine electrophilic Keap1-Nrf2 inhibitor that covalently binds to Keap1 can effectively enhance the antioxidant defense response, for example, dimethyl fumarate (Tecfidera) is clinically used to treat multiple sclerosis and psoriasis." (PMID 40179791, 2025). "The pharmacological inhibition of KEAP1 has been a major area of research, leading to the development of omaveloxolone and dimethyl fumarate (DMF)—approved KEAP1 inhibitors used to treat Friedreich's Ataxia, psoriasis, and multiple sclerosis, respectively." (PMID 40646550, 2025). "Dimethyl fumarate (DMF), an approved drug for multiple sclerosis, can disrupt the KEAP1–Nrf2 interaction by binding to cysteine residues within KEAP1, allowing Nrf2 translocation to the nucleus and Nrf2 transactivation of target genes by binding to their AREs." (PMID 38383481, 2024). "Highly reactive ligands, such as the approved drugs used for the treatment of multiple sclerosis, have been described to covalently bind to cysteines within the BTB domain of the E3 ligase Keap1." (PMID 41102521, 2025). "Our data revealed KEAP1, the molecular target of DMF, a drug approved for multiple sclerosis and psoriasis, as a functional DEG in H5N1-infected A549 cells." (PMID 32176725, 2020). "By modifying cysteine residues in KEAP1, oxidative stress, or electrophilic compounds like dimethyl fumarate (DMF), an FDA-approved drug for treatment of multiple sclerosis, disrupt KEAP1-NRF2 binding, leading to NRF2 accumulation." (PMID 31554934, 2019).
liver fibrosis (18 papers, 2017 to 2025). "Activation of the KEAP1/NRF2 signaling pathway has been linked to oxidative stress damage in liver fibrosis in several studies." (PMID 35721561, 2022). "Moreover, the upregulated expression of Keap1 together with deactivation or deficiency of Nrf2 aggravates hepatic fibrosis via ROS and activation of HSCs." (PMID 38303002, 2024). "Consequently, to determine the efficacy of YJSB and the mechanism of action of Kelch-like ECH-associated protein 1 (Keap1)-nuclear factor erythroid 2-related factor 2 (Nrf2) pathway against liver fibrosis." (PMID 37229248, 2023). "For example, miR-200a can regulate the Keap1/Nrf2 pathway in HSCs and hepatic fibrosis through the association of Nrf2 with Keap1, which results in cytoplasmic Nrf2 degradation and interference with induction of genes that encode antioxidant enzymes, such as NQO1." (PMID 28538690, 2017). "In addition, the mechanism of SZ-A ameliorating oxidative stress and hepatic fibrosis in MAFLD model mice might be associated with PGC1α-induced KEAP1/NRF2 axis activation." (PMID 39458927, 2024). "The TLR4/NF-κB pathway (β = 0.570) directly promoted liver fibrosis, whereas the Nrf2/Keap1 pathway (β = −0.486) inhibited it (P < 0.01)." (PMID 40826133, 2025). "PQ and Tau primarily affected liver fibrosis through three key nodes: the Nrf2/Keap1 pathway, the TLR4/NF-κB pathway, and tight junction proteins and mucin genes." (PMID 40826133, 2025). "We performed experimental validation of the Keap1 and Nrf2 proteins to investigate the underlying mechanisms of YJSB against mechanisms that cause CCl4-induced liver fibrosis." (PMID 37229248, 2023). "In conclusion, the KEAP1/NRF2 signaling pathway is a promising therapeutic target for hepatic fibrosis." (PMID 35721561, 2022). "The antioxidant ability of the liver is increased when Nrf2 separates from Keap1 during oxidative stress, leading to the synthesis of antioxidize and phase II detoxification enzymes, which can prevent liver fibrosis." (PMID 36232707, 2022). "Meanwhile, double-knockdown of PHD1 and Keap1 in mice alleviated liver fibrosis, and the effect was further enhanced especially in the preventive group." (PMID 29899699, 2018). "In this study, PHD1shRNA and Keap1shRNA plasmids were simultaneously transfected into the mice with liver fibrosis via hydrodynamic injection, and the subsequent effects of PHD1 and Keap1 on the prevention and reversal of liver fibrosis were observed." (PMID 29899699, 2018). "Accordingly, for the present study we used shRNAs to simultaneously knockdown the expressions of PHD1 and Keap1 in the hepatocytes with the aim of exploring therapeutic target for liver fibrosis." (PMID 28539891, 2017). "In addition to the histological assessments, the protein levels of the liver fibrosis markers KEAP1 and α-SMA were significantly elevated in the HFD group compared to the CTRL group (p < 0.05), indicating increased fibrotic activity." (PMID 39458927, 2024). "It was suggested that SZ-A might counteract liver oxidative stress and liver fibrosis induced by HFD through the KEAP1/NRF2/ARE axis." (PMID 39458927, 2024). "We wanted to see if YJSB could treat CCl4-induced liver fibrosis by regulating the Keap1-Nrf2 signaling pathway." (PMID 37229248, 2023). "The mechanism might be related to its ability to activate the Keap1-Nrf2 signaling pathway, regulate oxidative stress response, and play an anti-hepatic fibrosis role." (PMID 37229248, 2023). "The effect of GDK on chronic liver injury may be through the activation of the Keap1/Nrf2 pathway and inhibition of ferroptosis, alleviating liver fibrosis and abnormal functional changes." (PMID 36421420, 2022). "Thus, this indicates that interfering with the expression of PHD1 and Keap1 in the hepatocytes has obvious preventive effect against the CCl4-induced hepatic fibrosis." (PMID 29899699, 2018).